IL10 (interleukin 10)
Diseases named in the same sentence as IL10 in open-access papers (continued):
Sharing a sentence is not in itself a finding about the gene and the disease.
food allergy (continued). "The results indicate that the A20 levels and IL-10 levels in peripheral B cells were lower in food allergy (FA) patients than in healthy subjects." (PMID 27825134, 2016). "In the present study, we demonstrated that PANE increased the infiltration of IL-10-producing MDSC in the intestine of mice with food allergy." (PMID 23816049, 2013). "We therefore wondered whether the effects of IL-10 on MCs may be regulated by IL-33 signaling and investigated the role of IL-10 on MC activation and function during food allergy development in ST2-/- mice." (PMID 39935481, 2025). "Taken together, these data suggest that the reduced MC responses in both ST2-/- mice and anti-IL-10-treated WT mice during food allergy occur irrespectively of IgE levels and may result directly as a consequence of functional deficiencies in MCs." (PMID 39935481, 2025). "Furthermore, the transfer of either IL-10-producing CD4+ T cells or WT MCs restored the development of food allergy in IL-10-/- mice." (PMID 39935481, 2025). "Furthermore, we and others have shown that various Th2-derived cytokines such as IL-3, IL-4, IL-9 and IL-10 can have critical roles in promoting MC activation and function during food allergy." (PMID 39935481, 2025). "Therefore, apart from TFR cells being a key source of IL-10 that can promote IgE in food allergy, TFR cells are also a key source of IL-4 that can promote IgE in food allergy." (PMID 39377224, 2024). "While both IL-4 and IL-10 are important in this food allergy model, IL-4 is a primary regulator of IgE and may play a more dominant role in the IgE response than IL-10." (PMID 39377224, 2024). "Whether TFR cell–derived IL-10 explains the helper role of TFR cells in food allergy or whether there are other mechanisms used by TFR cells to promote the IgE response in food allergy is unclear." (PMID 39377224, 2024). "Recently, Maeta and collaborators demonstrated that continuous RA intake under allergen exposition improved the symptoms of food allergy in mice and may promote the induction of anti-inflammatory cytokines, such as IL-10 and IFN-γ." (PMID 35565735, 2022). "The low IL-10 levels in our study implied that excessive sodium may indirectly skew Th2 polarization by attenuating the Treg function in the mouse model of food allergy." (PMID 34835940, 2021). "The implications of IL-10 for the onset of food allergies were noted in a study using Il10-/- mice." (PMID 34067047, 2021). "For example, IL-10 can enhance IgE-mediated MC-dependent barrier dysfunction during food allergy." (PMID 32958528, 2020). "This variety in receptor expression suggests mast cells respond differently, such as in the gut where immunosuppressive IL-10 stimulates the development of food allergy or in the lungs where transforming growth factor-β1 (TGF-β1) can enhance mast cell IL-6 production." (PMID 32098318, 2020). "CITRUS did not detect expression of the Th2 cell cytokines IL-5, IL-10, or IL-13, cytokines that are strongly associated with food allergy." (PMID 32698761, 2020). "This indicates that lowering IL-10 concentrations in a murine OVA-induced food allergy model might be beneficial." (PMID 31349704, 2019). "Some studies have also documented decreased T-regulatory cells in humans with food allergy, suggesting this may be the reason for the documented decreased IL-10 and increased IL-4 concentrations in these patients." (PMID 31164117, 2019). "Taken together, mesenteric IL-10-producing regulatory B cells control food allergy via Foxp3+ regulatory T cells and could potentially act as a therapeutic regulator for food allergy." (PMID 26785945, 2016). "To further investigate the crosstalk between IL-10 and IL-33, and whether IL-10’s effects on IgE-induced MC responses may depend on IL-33, we assessed the development of food allergy in WT and IL-10-depleted ST2-/- mice using an ovalbumin (OVA)-induced model of intestinal anaphylaxis." (PMID 39935481, 2025).
food allergy (continued). "Furthermore, while both IL-33 and IL-10 may act as independent variables that regulate MC function during food allergy, these data also point to a potential for synergistic control if it were necessary." (PMID 39935481, 2025). "Overall, our data suggest that IL-10 may help prime mast cells during IgE-mediated food allergy." (PMID 35769569, 2022). "IL-10 deficient mice displayed decreased Th2 cytokine responses, loss of gastrointestinal mast cell accumulation, and reduced anaphylaxis in a food allergy model, which was reversed by the adoptive transfer of IL-10 expressing WT BMMCs but not IL-10 deficient BMMCs." (PMID 36142776, 2022). "However, in a murine model for OVA-induced food allergy, it was shown that IL-10 could also have proinflammatory effects." (PMID 31349704, 2019). "In addition, the population and percentage of IL-10-producing CD5+ B cells were significantly elevated by CIA and more so in OT mice, suggesting again that IL-10-producing CD5+ B cells in MLN are possibly associated with the regulation of food allergy in mice." (PMID 26785945, 2016). "Overall, our results suggest that IL-10-producing CD5+ B cells are associated with development of oral tolerance for foods and may provide new insight on therapeutic approaches for treatment of food allergies." (PMID 26785945, 2016). "In patients with food allergies and ulcerative colitis, CD19+CD25+CD71+CD73- regulatory B cells produce less IL-10 compared to the control group." (PMID 39767628, 2024). "A previous study demonstrated that HMO treatment elevated the production of IL-10 and decreased the production of TNF-α in mouse mast cells, thereby alleviating the symptoms of food allergy." (PMID 37372011, 2023). "Compared to raw milk, pasteurized milk also increased the production of IL-10, which was previously shown to act as a Th2 cytokine in this OVA-induced food allergy model." (PMID 31262028, 2019). "Conversely, studies in humans and mice with food allergy have demonstrated increased IL-4 and TNF-alpha and decreased IL-10 concentrations." (PMID 31164117, 2019). "Levels of INF-γ, IL-10 and TGF-β1 in the food allergy group were decreased compared with the counterparts of the control group." (PMID 28250847, 2017). "In the absence of IL-10, food allergy development was attenuated, leading to decreased MC expansion and IgE-mediated MC activation." (PMID 39935481, 2025). "Our data demonstrate that IL-10 enhances MC responses in both WT and ST2-/- mice, suggesting that IL-33 signaling is not required for IL-10’s effects either during IgE-mediated MC activation or food allergy." (PMID 39935481, 2025). "In this study, we demonstrate that IL-10 is able to regulate IgE-mediated MC proliferation and activation as well as MC responses during food allergy even in the absence of IL-33 signaling, suggesting that IL-33 is dispensable for IL-10’s effects." (PMID 39935481, 2025). "Non-IgE-mediated food allergy is believed to be cellular-dependent with a delayed response and a possible mechanism including IL10 and IL5." (PMID 39085570, 2024). "Another study relating to food allergy showed that EVs carry the allergen-MHC class 2 complexes and IL-10 and could induce Tr1 differentiation in healthy CD4+ T cells." (PMID 38674077, 2024). "Although TFR cells are generally thought to repress GC B cells and the Ab response, we have previously shown that in a mouse food allergy model, TFR cells produce IL-10 and play an essential helper role such that in the absence of TFR cells, IgE responses are diminished." (PMID 39377224, 2024). "This is the first study that aims to detect the expression of Th2 cytokines (IL-4, IL-5, IL-10, and IL-13) in infants with non-IgE food allergy and to compare it to peer healthy subjects." (PMID 35458127, 2022). "Our data revealed that values of IL-4 and IL-13 are higher in infants with non-IgE-mediated food allergies, whereas IL-5 and IL-10 are lower, as observed in IgE-mediated food allergies." (PMID 35458127, 2022).
food allergy (continued). "OVA-sensitized mice were protected from food allergy anaphylactic death by 60% and observed with significantly suppression of OVA-specific IgE,IL-17, TH2 cytokines (IL-4, IL-5, IL-10, IL-13) and TH1 cytokines (IFN-γ and IL-12) with the treatment of 25 mg/kg of extract." (PMID 31275149, 2019). "Non-IgE-mediated food allergy was also observed at higher frequency in ASD subjects with high/low IL-1ß/IL-10 ratios than with normal ratios." (PMID 29178897, 2017). "Given that peanut allergy, unlike most food allergies, is typically life long, we also sought evidence of age-related differences in plasma IL-10 levels." (PMID 20567520, 2010). "However, Il10-/- mice failed to develop the pathology of food allergy, and the number of activated MCs in Il10-/- mice was significantly lower than that in WT mice." (PMID 34067047, 2021). "The 6 dogs with confirmed CE and IL-4:IL-10 above the 95% CI of the mean of the non-GI group had a cytokine profile that may suggest a GI food allergy based on the studies performed in human and mouse models of GI food allergy." (PMID 31164117, 2019). "In addition, we could not link splenic ex vivo IL-10 levels to the presence of Tregs in both food allergy models." (PMID 29021893, 2017).
allergic rhinitis (48 papers, 2012 to 2026). Inflammation of the nasal mucous membranes caused by an IgE-mediated response to external allergens. "Splenocytes isolated from the DP-induced allergic rhinitis mouse model exhibited significantly increased IL-4, IL-10, IFN-γ, and TNF-α levels after stimulation with DP." (PMID 39335479, 2024). "MSCs and IL-10-MSCs were co-cultured with CD4+ T cells from patients with allergic rhinitis (AR), and the levels of Th2 cells and corresponding type 2 cytokines were studied." (PMID 38093354, 2023). "SST decreased the synthesis of IgE and IL-10 in mononuclear cells of peripheral blood obtained from patients with perennial allergic rhinitis due to Dermatophagoides farinae." (PMID 36297517, 2022). "Another study (with mice) showed that Clostridium butyricum extracts—again, postbiotics—can efficiently inhibit experimental allergic rhinitis by increasing IL-10 expression in B cells." (PMID 33799367, 2021). "Although the title of the paper mentions probiotics, the study was in fact performed with postbiotics since it was lyophilized extracts of bifidobacteria which were shown to suppress allergic rhinitis in mice via inducing IL-10-producing B cells." (PMID 33799367, 2021). "After PAR-2 activation, signalling through Bcl2L12 leads to IL-10 transcription repression and reduced IL-10-expression by B cells from patients with allergic rhinitis." (PMID 34566974, 2021). "Application of A. cepa on the nasal cavity of BALB/c mice with allergic rhinitis revealed remarkable decreases in IgE and inflammatory cytokines IL-4, IL-5, IL-10, and IL-13." (PMID 34552650, 2021). "IL-10 is expressed on epithelial and endothelial cells of nasal mucosa in patients affected by allergic rhinitis and IL-10 serum levels are observed to be significantly lower in asthmatic patients compared to healthy controls." (PMID 32194407, 2020). "Acupuncture dramatically reduces IL-4 and IL-10 and upregulates IFN-γ in allergic rhinitis patients, causing a swift of Th1/Th2 balance towards Th1." (PMID 33144870, 2020). "The serum levels of IL-5 and IL-10 in complication group significantly exceeded those of allergic rhinitis group (P<0.05)." (PMID 30344593, 2018). "The serum levels of IL-5 and IL-10 in the complication group were significantly higher than those of the allergic rhinitis group (P<0.05)." (PMID 30344593, 2018). "In summary, the present study indicated that high levels of miR-19a and low levels of IL-10 were observed in peripheral DCs in patients with nasal polyp and allergic rhinitis." (PMID 28388587, 2017). "In summary, the present data indicate that miR-146a can induce IL-10-producing Mos to suppress the skewed Th2 polarization, suggesting that miR-146a has the potential in the treatment of allergic disorders, such as allergic rhinitis." (PMID 26526003, 2015). "This endothelial IL-10 expression appeared to have a strong inverse correlation with the induced symptoms of allergic rhinitis." (PMID 24405811, 2014). "IL-10, an anti-inflammatory cytokine, is thought to suppress allergic reactions and may also be involved in the alleviation of allergic rhinitis." (PMID 40635887, 2025). "However, Guo M's study on the treatment of allergic rhinitis found that vitamin D use increased IL-10 in patients, which is different from the results of the current study." (PMID 40951891, 2025). "An intranasal instillation experiment of probiotic extracts in mice demonstrated that Clostridium butyricum extracts can inhibit allergic rhinitis by upregulating interleukin-10 (IL-10), providing a theoretical basis for the local therapeutic application of probiotics." (PMID 41465485, 2025). "Decreased PPG-stimulated IL-10 production, as well as decreased LPA-stimulated and PPG-stimulated FOXP3 expression, in cord blood were further identified as risk factors for a positive allergic status in children and allergic rhinitis (respectively)." (PMID 27646403, 2016).
allergic rhinitis (continued). "In the present study, on the basis of immunohistochemical findings, elaborations were made on two possible ways in which endothelial IL-10 expression could play a role in symptoms of allergic rhinitis." (PMID 24405811, 2014). "Interleukin-10 (IL-10) has an important anti-inflammatory and immunoregulatory function, and its expression is negatively correlated with the development and severity of allergic rhinitis (AR)." (PMID 24568666, 2014). "A recent study, conducted in humans and mice, demonstrated that miR‐181a regulates the expression of IL‐10 and TGF‐β in allergic rhinitis." (PMID 36999032, 2023). "Generally, these data demonstrated the inhibitory effects of sEV‐mDCs on the type 2 responses partially by acting on the IL‐10/IL‐10Rα axis, further indicating the potential application of the cell‐free therapy of MSC‐sEV in the treatment of allergic rhinitis." (PMID 35415925, 2022). "The targets of 48 putative therapeutic components in the treatment of allergic rhinitis include IL6, TNF, CXCL8, ICAM1, ILA, MMP9, IL10, and IL1B." (PMID 31611923, 2019). "IL-10, IL-17, TGF-β, IFN-γ, IL-22, and IL-35 serum levels of allergic rhinitis (AR) patients were measured using ELISA method." (PMID 29692871, 2018). "It has also been shown that T cells producing IL-10- and IFN-μ increase in numbers during immunotherapy in allergic rhinitis patients." (PMID 26866695, 2016). "The inducible IL-10+ Mos showed an immune suppressor effect on the activities of CD4+ effector T cells and the Th2 polarization in a mouse model of allergic rhinitis." (PMID 26526003, 2015). "A recent human study comparing acupuncture with Loratadine for perennial allergic rhinitis reported an increase in mean values for interleukin-10 (IL-10), but the increase was not statistically significant, possibly due the study being underpowered." (PMID 26339274, 2015). "In patients with seasonal allergic rhinitis, under nasal allergen stimulation, the level of CCL13 in nasal secretions increases 3.7-fold, while IL-10 and IL-4 significantly decrease; CCL13 may worsen, while IL-10 may alleviate nasal mucosa allergy." (PMID 37153575, 2023).
B-cell lymphoma (48 papers, 2007 to 2026). "An increased susceptibility for B cell lymphoma has also been reported in patients with IL-10/IL-10R deficiency." (PMID 40376626, 2025). "To explore the possible association between IL-2-330T/G and IL-10-1082A/G single-nucleotide polymorphisms and the susceptibility to B-cell NHL (B-NHL) in Egyptians, we conducted a case-control study." (PMID 28713071, 2018). "The aim of the current work was to study the possible role of IL-2-330T/G (rs2069762) and IL-10-1082A/G (rs1800896) single-nucleotide polymorphisms (SNPs) as genetic risk factors for B-cell NHL (B-NHL) in a group of Egyptian patients." (PMID 28713071, 2018). "The nested case-control study found an increased risk of B cell NHL in women with increased levels of IL-10." (PMID 29228708, 2017). "In other B-cell NHL, large studies identified IL10 polymorphisms as significant risk factors for specific groups of NHL, such as diffuse large B-cell lymphoma." (PMID 23029361, 2012). "Additionally, IL-10/IL-10R deficiency patients have the risk of developing B-cell lymphoma." (PMID 27699073, 2016). "Produced by malignant B cells through a variety of mechanisms, IL-10 is a key cytokine in the pathogenesis of B-cell lymphoma, and is considered a biomarker of tumor load." (PMID 40468390, 2025). "In B-cell lymphomas, elevated levels of inflammatory cytokines such as IL-6, IL-10, VEGF, and IL-8 have been observed in patients with diffuse large B-cell lymphoma (DLBCL)." (PMID 40292253, 2025). "NFATc1 can also be activated by the B cell receptor (BCR) and upregulate the IL-10 chemokine to activate the JAK2/STAT3 pathway in B cell lymphoma cells, ultimately inducing PD-L1 expression." (PMID 37138354, 2023). "One potential explanation is that IL-10 works in autocrine/paracrine loops to induce the antiapoptotic effect in non-Hodgkin’s B-cell lymphoma." (PMID 35914074, 2022). "Taken together, these studies suggest that EBV can suppress miR-194 expression, leading to increased production of IL-10 and survival of B-cell lymphoma cell lines." (PMID 36304469, 2022). "While the T helper 2 (Th2) cells, LY-1+ (CD5+) are responsible for the production of IL-10 in mice, and CD4+ T cells, T cell clones, B cell lymphomas and mast cells are responsible for IL-10 production in humans." (PMID 36560690, 2022). "Apart from helper T cells, various cell types of the B cell lymphoma microenvironment are capable of producing the cytokines IL-4, IL-6, IL-10 and TNFα." (PMID 32899476, 2020). "MicroRNA-194 overexpression increases apoptosis of EBV(+) B-cell lymphoma lines and attenuates IL-10 production." (PMID 32457824, 2020). "B-cell lymphomas isolated from EBV(+) PTLD produce IL-10 in a constitutive way and use it as an autocrine growth factor." (PMID 32457824, 2020). "The increased levels of TNF-α, IL-12 and IFN-γ and undetectable levels of IL-4 and IL-10 suggest that TME in lacrimal gland B-cell lymphoma was polarized toward Th1 pattern, which is similar to what were previously observed with an intraocular B-lymphoma." (PMID 29029511, 2017). "Next we measured the serum levels of IL-10 from newly diagnosed B-cell NHL patients (diffuse large B-cell lymphoma: n=188; follicular lymphoma: n=234) and healthy donors (n=400) using a multiplex ELISA (Luminex)." (PMID 26230952, 2015). "Taken together, these results suggest that elevated IL-10 serum levels contribute to increased numbers of immunosuppressive CD14+HLA-DRlow/− monocytes in B-cell NHL." (PMID 26230952, 2015). "Supporting the role of IL-10 in facilitating CD14+HLA-DRlow/− cells in B-cell NHL, we observed that IL-10 pretreated monocytes exhibited suppressive properties by inhibiting activation and proliferation of T cells." (PMID 26230952, 2015). "Taken together, these results reveal a novel role for IL-10 in inducing immunosuppressive CD14+HLA-DRlow/− monocytes in B-cell NHL that significantly suppress T-cell function." (PMID 26230952, 2015).